CCR4 (C-C motif chemokine receptor 4)
Diseases named in the same sentence as CCR4 in open-access papers (continued):
Sharing a sentence is not in itself a finding about the gene and the disease.
dysplasia (2 papers, 2021 to 2024). A usually neoplastic transformation of the cell, associated with altered architectural tissue patterns. "The levels of Treg-associated chemokines/cytokines and the Treg-associated chemokine receptor Ccr4 were examined in dysplasia and SCC lesions." (PMID 33921389, 2021). "In laboratory experiments, isolated cells expressing CCL20 and CCR4, stimulated by IL-5 and IL-7, demonstrated an increased ability of CD8+ T cells to penetrate dysplastic cells, thereby improving therapeutic efficiency in fighting dysplasia." (PMID 39273632, 2024).
emphysema (2 papers, 2004 to 2021). "The loss of lung function in patients with COPD and emphysema is associated with a high percentage of CD4+ and CD8+ T lymphocytes that express receptors CCR5 and CXCR3, but not CCR3 or CCR4 (both markers of T helper one cells)." (PMID 33953665, 2021). "Flow cytometry revealed very low expression of CCR3 and CCR4 (1%–3%) in control (n = 10) and emphysema (n = 18) groups, and did not discriminate between these populations (data not shown)." (PMID 15526056, 2004).
esophageal cancer (2 papers, 2016 to 2019). A primary or metastatic malignant neoplasm involving the esophagus. "Statistically significant (p < 0.001) decreases in Tregs (CD3 + CD4 + CD25 + CD127low/−) were observed at 6, 168, and 336 h, as predicted based on data from a phase I study of single-agent mogamulizumab in patients with CCR4− lung and esophageal cancers." (PMID 31801624, 2019).
gastric adenocarcinoma (2 papers, 2020 to 2021). "Herein we showed that the Ccr4 and Caf1 deadenylases, which are key enzymes in cytosolic mRNA decay, were dysregulated in some types of cancers including stomach adenocarcinoma." (PMID 33671234, 2021). "In this study, we found that Ccr4 and Caf1, the major cytosolic deadenylases in eukaryotic cells, are dysregulated in several types of cancers including stomach adenocarcinoma." (PMID 33671234, 2021). "We found that human Ccr4 (hCcr4a/b) and Caf1 (hCaf1a/b), the dominant cytosolic deadenylases, were dysregulated in several types of cancers including stomach adenocarcinoma." (PMID 33671234, 2021). "In this research, we found that human Ccr4a/b (hCcr4a/b) and Caf1a/b (hCaf1a/b) deadenylases, the catalytic components of the Ccr4-Not complex, were dysregulated in several types of cancers including stomach adenocarcinoma." (PMID 33671234, 2021).
HCMV infection (2 papers, 2023 to 2025). "In this study, we identify a novel host function on which HCMV infection is dependent—CCR4‐NOT‐dependent mRNA deadenylation." (PMID 37846490, 2023). "We therefore conclude that the CCR4‐NOT complex regulates HCMV infection by its mRNA deadenylation function." (PMID 37846490, 2023). "To establish whether CCR4‐NOT complex components are altered in their abundance during HCMV infection, we monitored expression of nucleases CNOT6, 6L, 7, and 8 and nonenzymatic modules CNOT1, 2 3, by immunoblot where reliable antibodies could be sourced and RT‐qPCR where not." (PMID 37846490, 2023). "In agreement with this, AU-rich mRNAs, which are typically destabilized by mechanisms requiring CCR4-NOT, were found to be stabilized in HCMV infection in an RNA2.7-dependent manner." (PMID 41446155, 2025).
Hepatitis (2 papers, 2018 to 2020). Inflammation of the liver. "Consequently, disruption of the CCR4–NOT function through CNOT1 depletion induces aberrant gene expression that is associated with lethal hepatitis." (PMID 32238456, 2020).
Hypertension (2 papers, 2019 to 2024). The presence of chronic increased pressure in the systemic arterial system. "Finally, positive associations of CCR4+ T lymphocytes with hypertension link this cell subset with vascular inflammation." (PMID 39109081, 2024).
injury (2 papers, 2020 to 2025). Damage inflicted on the body as the direct or indirect result of an external force, with or without disruption of structural continuity. "Understanding these intricate immune responses and their regulation through chemokine receptors like CCR4 may provide new therapeutic opportunities for treating ICH‐induced brain injury." (PMID 39996481, 2025). "For example, CCR4 antagonist or modified CCL5 peptide reduced T cell and eosinophil infiltration and also attenuated AD-like skin injury." (PMID 32280674, 2020).
Intellectual disability (2 papers, 2019 to 2023). "SCAPER mutants that cause intellectual disability and retinitis pigmentosa in humans are impaired in CCR4-NOT recruitment, tubulin mRNA degradation, and microtubule-dependent chromosome segregation." (PMID 37295431, 2023). "CCR4-NOT complex is a highly conserved transcriptional regulator that is essential for neural development and differentiation of neural stem cells and has been featured in studies of the 7q33 deletion syndrome that is characterized by intellectual disability." (PMID 31620175, 2019).
leprosy (2 papers, 2016 to 2025). Leprosy is a chronic infectious disease affecting primarily the skin and peripheral nervous system. "Contacts of patients with leprosy are mainly associated with CXCR3/CCR4/HLA-DR and LL/BL patients with %B-06 (IgD+) and CCR6/CCR7." (PMID 40683203, 2025). "The surface expression of the chemokine receptor, CCR4 was also significantly high on Treg cells in leprosy patients with BL/LL." (PMID 26751584, 2016). "CCR4 serves as the receptor for CCL17 and CCL22, the latter displaying the most prominent difference in this study between contacts and patients with leprosy, with unprecedented discriminatory potential for BT/TT patients and contacts." (PMID 40683203, 2025).
lymph node metastasis (2 papers, 2019 to 2022). "It was also associated with lymph node metastasis by inducing an increase in CCR4 expression." (PMID 36380313, 2022). "In this study, we found that CCR2 and CCR4 were highly expressed in Nav1.6 high-expression CRC tissues and were positively correlated with lymph node metastasis." (PMID 31672162, 2019). "CCR2, CCR4, and their respective ligand-mediated pathways, CCR2\CCL2 axis and CCR4\CCL22 axis, are considered to be important mechanisms of lymph node metastasis." (PMID 31672162, 2019).
lymphoid neoplasm (2 papers, 2013 to 2019). A neoplasm composed of a lymphocytic cell population which is usually malignant (clonal) by molecular genetic and/or immunophenotypic analysis. "We have tried to review all the available publications regarding CCR4+ lymphoid neoplasms and adaptation of mogamulizumab treatment for such diseases as far as we could." (PMID 30968266, 2019).
MALT lymphoma (2 papers, 2015 to 2021). An indolent, extranodal type of non-Hodgkin lymphoma composed of small B-lymphocytes (centrocyte-like cells). "Interestingly, distinct mutation profiles, corresponding to clusters of nonsense and frameshift mutations in the C-termini of GPCRs, GPR34, CCR6, and CCR4, have been reported in mucosa-associated lymphoid tissue (MALT) lymphoma and adult T cell leukemia/lymphoma (ATLL) as gain-of-function mutations." (PMID 34852802, 2021). "One of our previous studies describes CCR4—a chemokine receptor genomically located on chromosome 3 (3p24)—highly expressed in trisomy 3 + MALT lymphoma whereas transcripts for this chemokine receptor were missing in trisomy 3− MALT lymphomas." (PMID 25922601, 2015).
nasopharyngeal carcinoma (2 papers, 2020 to 2023). A carcinoma arising from the nasopharyngeal epithelium. "Sengupta dataset (41 patient samples) evaluated that expression of IFIT1 (p = 5.38 × 10−5), CCR4 (p = 0.046), and CCL4 (p = 2.79 × 10−8) genes were increased in nasopharyngeal carcinoma compared with normal nasopharynx." (PMID 32961854, 2020).
neuropathy (2 papers, 2020 to 2021). A disorder affecting the nervous system that manifests with pain, tingling, numbness, and/or muscle weakness. "In light of subsequent research, we propose that CCR4 is a promising potential target for the pharmacotherapy of painful neuropathy." (PMID 32760393, 2020). "Because neuroimmune interactions are important in the development of neuropathy and considering the promising results obtained in our biochemical studies, we suggest that the pharmacological blockade of CCR4 may represent a new strategy for neuropathic pain polytherapy in the future." (PMID 32760393, 2020). "Moreover, taking into consideration our results and aforesaid literature, all three chemokines acting via CCR4, that is, CCL17, CCL22, and CCL2, seem to be important mediators in pathological nociceptive processes at the DRG level under neuropathy." (PMID 32760393, 2020).
oral cancer (2 papers, 2021 to 2024). "The expression of CCR4, CXCR3, CCR2, and CCR8 was higher in highly invasive oral cancer cell lines (SCC-25, CAL-27, and FaDu) than in the less aggressive cell line (HSC-2), whereas CCL19 and P2RY14 expression showed the opposite trend." (PMID 38213736, 2024). "We further examined the expression of CCR4, CXCR3, P2RY14, CCR2, CCR8, and CCL19 in highly aggressive oral cancer cell lines and tissues." (PMID 38213736, 2024). "Specifically, these findings indicate that CCR4, CXCR3, CCR2, and CCR8 may affect the invasiveness of oral cancer cells." (PMID 38213736, 2024). "Further analysis of gene expression in clinical tissues revealed that CCR4, CXCR3, CCR2, and CCR8 exhibited higher expression in oral cancer cells of patients with metastasis compared to those without, whereas CCL19 and P2RY14 displayed the opposite trend." (PMID 38213736, 2024).
oral squamous cell carcinoma (2 papers, 2018 to 2022). "A low stromal CD8/CCR4 Treg ratio was an independent prognostic factor for lower survival in oral squamous cell carcinoma." (PMID 30153850, 2018). "CCR4+CD3+CD8+ cells were identified in the stroma and tumor nest of patients with oral squamous cell carcinoma (OSCC) (white arrow)." (PMID 36522365, 2022).
pituitary adenoma (2 papers, 2024 to 2025). "In pituitary adenoma, lactate activates the mTOR pathway in TAMs, leading to increased secretion of C-C motif chemokine ligand 17 (CCL17), which binds to C-C motif chemokine receptor 4 (CCR4) on tumor cells and promotes invasion." (PMID 41152975, 2025).
respiratory failure (2 papers, 2021 to 2022). The significant impairment of gas exchange within the lungs resulting in hypoxia, hypercarbia, or both, to the extent that organ tissue perfusion is severely compromised. "Presumably, CCR4 expressing T cells migrate to the pulmonary system, which leads to respiratory stress and even respiratory failure." (PMID 33784417, 2021).
triple-negative breast carcinoma (2 papers, 2020 to 2022). An invasive breast carcinoma which is negative for expression of estrogen receptor (ER), progesterone receptor (PR), and human epidermal growth factor receptor 2 (HER2). "In addition, a CCR4 inhibitor restrained triple-negative breast cancer progression by reducing myeloid-derived immunosuppressor cell recruitment, angiogenesis and metastasis." (PMID 33318300, 2020).
tuberculous pleurisy (2 papers, 2011 to 2013). "Recent findings suggest that the immunogenic reaction in tuberculous pleurisy involves lymphocytes (including CD3, CD4, CCR4, and Th17 cells), neutrophils, mesothelial cells, and various cytokines such as interferon-γ, interleukin (IL)-8, IL-12, and monocyte chemoattractant protein-1." (PMID 23317113, 2013). "Elevated CD3, CD4, CCR4 and Th17 cells and decreased mast cells and GATA-3+ cells in the parietal pleura distinguish patients with untreated tuberculous pleurisy from those with nonspecific pleuritis." (PMID 21829471, 2011). "The number of CD3+, CD4+ and CCR4+ cells and the expression of RORC2 mRNA were significantly increased in the tuberculous pleurisy patients compared with the nonspecific pleuritis subjects." (PMID 21829471, 2011).
adenoma (1 paper, 2024). A neoplasm arising from the epithelium. "Moreover, the upregulated Th2 cells, identified by the CCR4 expression in the tissue-derived CD4+T cells, from adenoma to CRC were consistent with the peripheral CD4+IL-4+ Th2 response." (PMID 38343544, 2024).
Adenovirus infection (1 paper, 2023). "Adenovirus infection also results in degradation of select CCR4‐NOT components favoring replication." (PMID 37846490, 2023).
Atherosclerotic lesion (1 paper, 2025). A lesion associated with atherosclerosis, a multifactorial and multipart progressive disease manifested by the focal development within the arterial wall of lesions, that ranges from the development of a fatty streak, plaque progression, and plaque disruption. "Our data show that interactions between CCR4 and CCL17/CCL22 may promote Treg-skewed responses in lymphoid tissues and atherosclerotic lesions." (PMID 40608058, 2025).
autism (1 paper, 2021). Persistent deficits in social interaction and communication and interaction as well as a markedly restricted repertoire of activity and interest as well as repetitive patterns of behavior. "Heterozygous loss-of-function variants in CNOT3, encoding a subunit of the CCR4-NOT protein complex, have recently been reported to cause a syndromic condition known as intellectual developmental disorder with speech delay, autism and dysmorphic facies (IDDSADF)." (PMID 34208845, 2021).
autoimmune encephalitis (1 paper, 2022). Inflammation of the brain secondary to an immune response triggered by the body itself. "An increase in CCL22 and CCR4 expression was demonstrated in the central nervous system in mice that develop chronic recurrent forms of autoimmune encephalitis, which demonstrates the involvement of CCL17/CCL22/CCR4 in the pathogenesis of this disease." (PMID 36555280, 2022).
bacterial sepsis (1 paper, 2010). "In this respect, our findings are consistent with the protective role of CCR4 in the pathogenesis of bacterial sepsis." (PMID 21206747, 2010).
brain hemorrhage (1 paper, 2022). "CCL17 depended on CCR4 activation regulating the PI3K/AKT/FOXO1 signaling pathway to reduce neuronal inflammation and apoptosis after brain hemorrhage." (PMID 35800988, 2022).
breast invasive cancer (1 paper, 2022). "Our t-SNE study of TCGA data from patients with breast invasive cancer reveals that high CCR4 expression in tumor tissue is linked to high FOXP3 expression." (PMID 35222362, 2022). "The t-SNE analysis of TCGA data from patients with breast invasive cancer also revealed a strong connection between CCR4 and FOXP3, which was further validated in our laboratory." (PMID 35222362, 2022).
Chronic colitis (1 paper, 2016). A chronic inflammatory disease of the large intestine (colon, cecum and rectum). "However, in the chronic colitis model, increased expression of both CCR4 and Foxp3 was detected in CD200tg mice, with an increased ratio of Foxp3+:CD3+ cells enumerated in the same CD200tg mice both in colonic tissue sections and by FACS staining of isolated mesenteric lymph node cells." (PMID 26841120, 2016).
chronic hepatitis B (1 paper, 2023). "We examined the expression of CCR4 on different subsets of T cells including CD4 and CD8 in chronic hepatitis B (CHB) patients and compared it with HBV-vaccinated healthy controls (Vacc-HC)." (PMID 37081509, 2023).
chronic kidney disease (1 paper, 2015). Impairment of the renal function secondary to chronic kidney damage persisting for three or more months. "The study aimed at flow cytometric analysis of T cell subsets with selected surface chemokine receptors (CCR4, CCR5, CCR7, CXCR3, and CXCR4) or receptor combination in peripheral blood of children with chronic kidney disease (CKD) on hemodialysis (HD)." (PMID 25866451, 2015).
cutaneous lupus erythematosus (1 paper, 2020). An autoimmune disorder that manifests as different lupus-specific skin disorders; it can occur with systemic lupus erythematosus, or as a singular disease. "Additionally, significant numbers of CD8+/CCR4+ T lymphocytes were identified in skin biopsies of patients with cutaneous lupus erythematosus (CLE) and correlated with aggressive skin scarring." (PMID 32973504, 2020).
cyst (1 paper, 2018). A sac-like closed membranous structure that may be empty or contain fluid or amorphous material. "Taken together, we can conclude that pgc is regulated by Nos, Pum, and Twin from GSCs to the 4-cell cyst stage via the CCR4-Not complex." (PMID 30590052, 2018).
endotoxemia (1 paper, 2015). "Using a complex animal model of polymicrobial abdominal sepsis (CLP), our results corroborate with those reported in the literature using different models, such as endotoxemia and CASP, which have also demonstrated a more effective innate immune response in CCR4-/- mice." (PMID 26197455, 2015).
eye cancer (1 paper, 2018). "Here, we use different Drosophila melanogaster eye cancer models to study the potential tumor suppressor function of Not3, the CNOT3 orthologue, and other members of the CCR4-NOT complex." (PMID 30144809, 2018).
Fabry disease (1 paper, 2024). Fabry disease (FD) is a progressive, inherited, multisystemic lysosomal storage disease characterized by specific neurological, cutaneous, renal, cardiovascular, cochleo-vestibular and cerebrovascular manifestations. "Furthermore, patients with Fabry disease exhibit elevated blood lymphocyte counts, increased levels of specific T cytotoxic cell subsets (CCR4+CXCR3+ and CCR6+), higher numbers of MHCII+ CD1d+ CD11b+ CD31+ monocytes, and notable tissue infiltration by macrophages and B cells." (PMID 39596318, 2024). "Moreover, studies observed an increase in blood lymphocyte counts, with notable elevations in specific T cytotoxic cell subsets (CCR4+CXCR3+ and CCR6+), as well as the presence of MHCII+ CD1d+ CD11b+ CD31+ monocytes in patients with Fabry disease." (PMID 39596318, 2024).
Fanconi anemia (1 paper, 2018). Fanconi anemia (FA) is a hereditary DNA repair disorder characterized by progressive pancytopenia with bone marrow failure, variable congenital malformations and predisposition to develop hematological or solid tumors. "Among these are polymerase (DNA directed), epsilon, catalytic subunit (POLE); PTEN; Fanconi anemia, complementation group A (FANCA); and CCR4-NOT transcription complex, subunit 3 (CNOT3) and others." (PMID 30143704, 2018).
gastritis (1 paper, 2022). Inflammation of the stomach. "The CCR4+/CD3+ ratio in the antrum was higher in the active gastritis group than in the inactive gastritis group (23.4 ± 13.4% vs. 9.6 ± 9.8%)." (PMID 35735608, 2022).
graft versus host disease (1 paper, 2023). An immune system disorder that occurs after allogeneic hematopoietic stem cell transplant and is a reaction of donor immune cells against host tissues. "As CCR4 is highly expressed on regulatory T cells as well as ATLL cells, pre-transplant MOG induces severe graft-versus-host disease (GvHD)." (PMID 36083572, 2023).
Granuloma (1 paper, 2020). A compact, organized collection of mature mononuclear phagocytes, which may be but is not necessarily accompanied by accessory features such as necrosis. "Hence, the enhanced immunosuppressive activity induced by fucoidan may be related to the functional expressions of CCR4 and CXCR5 on Treg cells, thus relieving the hepatic inflammatory response and resultant process of granuloma and fibrosis." (PMID 32894174, 2020).
Graves disease (1 paper, 2016). Graves' disease is an autoimmune disorder that leads to overactivity of the thyroid gland (hyperthyroidism).It is caused by an abnormal immune system response that causes the thyroid gland to produce too much thyroid hormones. "They concluded that RANTES (regulated on activation, normal T cells expressed and secreted) in interaction with its receptors (CCR1, CCR3, CCR4, and CCR5), mainly on the lymphocytes, may be involved in the maintenance of lymphocytic infiltration and the autoimmune responses in Graves' disease." (PMID 27872865, 2016).
Hepatic steatosis (1 paper, 2025). Steatosis is a term used to denote lipid accumulation within hepatocytes. "More recently, some studies pointed out the benefits of some CCR4-NOT inhibitors against hepatic steatosis." (PMID 39941720, 2025).